IL2 (interleukin 2)
Diseases named in the same sentence as IL2 in open-access papers (continued):
Sharing a sentence is not in itself a finding about the gene and the disease.
pulmonary TB (25 papers, 2012 to 2025). "To address this concern, we performed a prospective multicentre diagnostic study to evaluate the combined IFN-γ and IL-2 release assay for detect active pulmonary tuberculosis in China." (PMID 34217302, 2021). "IFN-γ/IL-2 ratios in serum showed a potential diagnostic value for detecting extra-pulmonary tuberculosis." (PMID 28033330, 2016). "Decreased IL-2 production in humans has been shown to be associated with susceptibility to infections such as cytomegalovirus, Cryptococcus neoformans, Onchocerca volvulus and pulmonary tuberculosis." (PMID 25329064, 2014). "Studies at home and abroad have shown that IL-2 in active pulmonary TB is substantially inferior to that in healthy individuals, and IL-2 is low in both new and old pulmonary TB." (PMID 38650928, 2024). "Regarding extrapulmonary TB, lower levels of IFN-γ, IL-2, IL-10 and IL-17 were observed in patients in this group compared with pulmonary TB." (PMID 36296351, 2022). "Several studies have demonstrated the presence of functional Mtb-specific CD4+ T cell responses in treatment-naïve pulmonary TB patients by assessing the production of IL-2, TNF-α, and IFN-γ in PBMCs stimulated with Mtb antigens." (PMID 29983703, 2018). "IL-2 and IL-21 have been shown to be important to host resistance in animal models and regulation of these cytokines has been demonstrated in human pulmonary TB." (PMID 32373129, 2020). "The aim of our study was to investigate whether IL6–174 G>C SNP and IL17A -197 G>A polymorphism and additional cytokine genes involved in immune response to MTB (IL2, IL4, IL10, IFNG and TNF) are associated with genetic susceptibility to pulmonary TB (PTB)." (PMID 26840977, 2016). "An independent-samples t-test showed an increased frequency of CD4+ T cells expressing IFN-γ (p = 0.034) and a significantly decreased frequency of CD4+ T cells expressing IL-2 (p = 0.037) - both ESAT-6 specific - in patients with pulmonary TB when compared to diseases other then TB." (PMID 22523581, 2012). "IL-2 could restore T-cell anergy in patients with pulmonary tuberculosis." (PMID 31632413, 2019). "In the comparison of median cytokine levels between patients with pulmonary TB and extrapulmonary TB, the extrapulmonary TB group had significantly lower levels of IFN-γ (p < 0.0001), IL-2 (p = 0.0368), IL-10 (p = 0.0373) and IL-17 (p = 0.0326)." (PMID 36296351, 2022). "As highlighted previously, our findings indicate that monitoring acute phase parameters (ESR, CRP), Th1 cytokines (IL-2) and anti-inflammatory (IL-4) may help understanding the multidimensionality of immunopathology in TB and point to novel potential therapeutic targets for pulmonary TB." (PMID 27494953, 2016). "We also noted that Ag85A, ESAT-6, PPD and H37Rv curtailed TCR/CD28 induced binding activity of NFAT on IL-2 promoter in PPD+ve healthy individuals and pulmonary TB patients both." (PMID 26552486, 2015). "The classical cytokines such as IL-2, TNF-α, IL-6 and IFN-γ, have been reported to correlate with disease activity during active pulmonary TB." (PMID 23626814, 2013). "Differences between pulmonary TB and other diseases were restricted to increased frequencies of CD4+IFN-γ+ T cells and decreased frequencies of CD4+IL-2+ T cells, contributing independently to the logistic regression model." (PMID 22523581, 2012). "The highest AUCs to discriminate between pulmonary TB and other diseases −0.704 and 0.654 - were the ratios of IFN-γ divided by IL-2, induced by PPD and ESAT-6, respectively." (PMID 22523581, 2012). "It was reported that the synthesis of cytokines in pulmonary TB with DM patients showed significant changes compared to pulmonary TB without DM, such as IL-2, IL-6, IL-17, TNF-α and IFN-γ." (PMID 38027218, 2023). "It was reported that the synthesis of cytokines in pulmonary TB with DM patients shown significant changes compared to pulmonary TB without DM, such as IL-2, IL-6, IL-17, TNF-α and IFN-γ." (PMID 34134685, 2021).
pulmonary TB (continued). "The frequency of IFN-γ- (1.5-fold, p = 0.026) and IL-2- (2.1-fold, p = 0.002) producing cells was significantly higher in the blood of diabetic than in that of non-diabetic pulmonary tuberculosis patients." (PMID 27783671, 2016). "We also examined whether neutralizing the IL-6 receptor affected PPD-induced changes in the frequency of IFN-γ-, IL-2-, TNF-α-, and IL-17A-producing cells in pulmonary TB patients with T2DM." (PMID 27783671, 2016). "Assessment of the TNF-α/IL-2 ratio derived of CD4+ T cells revealed increased TNF-α in patients suffering from extra-pulmonary TB, suggesting a more pro-inflammatory cytokine profile if compared to pulmonary TB." (PMID 22523581, 2012). "The following cytokine ratios were found to be different between non-TB diseases and pulmonary TB: PPD induced IFN-γ/IL-2 (p<0.001) and ESAT-6 induced TNF-α/IFN-γ (p = 0.048)." (PMID 22523581, 2012). "Our objective was to study calcium mobilization, activation of MAPKs and binding of NFAT and NFκB on IL-2 promoter in peripheral blood mononuclear cells (PBMCs) of pulmonary TB patients and healthy individuals in presence or absence of M. tuberculosis antigens." (PMID 26552486, 2015). "The frequency of IFN-γ- (1.7-fold, p = 0.0002), IL-2- (2.1-fold, p = 0.0001), TNF-α- (1.6-fold, p = 0.0005), and IL-17A- (2-fold, p = 0.0004) producing cells was significantly higher in diabetic than in non-diabetic pulmonary TB patients." (PMID 27783671, 2016).
bladder cancer (24 papers, 1991 to 2025). "Combined cytokine therapy was conducted with orthotopic bladder cancer in mice using a recombinant murine IL-12 and human IL-2." (PMID 40699676, 2025). "Dosing presents a complication in IL-2 treatment in bladder cancer and contributes to its limited therapeutic index." (PMID 40699676, 2025). "Cytokines like IL-2, IL-8, and IL-12 have shown potential in bladder cancer therapy and remain important areas of research." (PMID 40699676, 2025). "The aberrant high-level of BACH1-IT2 in bladder cancer significantly inhibited immune activation in our in vitro co-culture system as indicated by secretion of both IL-2 and TNF-α." (PMID 38468240, 2024). "Earlier investigations not only found IL-2 application to be effective in treating bladder cancer, but also showed the expression of the interleukin-2 receptor (IL-2R) on many different tissue cell lines of the body." (PMID 33027905, 2020). "Our study aims to contribute to the completion of the understanding of the IL-2 impact in therapeutic approaches, especially bladder cancer." (PMID 33027905, 2020). "Many studies have confirmed the effectiveness of IL-2 applied intravesically for bladder cancer immunotherapy." (PMID 33027905, 2020). "The human interleukin-2 (IL-2) surface modified MB49 bladder cancer cells vaccine induced specific antitumor immunity and was effective against metastatic bladder cancer in our previous study." (PMID 26566931, 2015). "Unexpectedly, no substantial changes were observed, indicating that, once IL-2 activated, NK cells from healthy donors respond to bladder cancer cells independently of the presence of BCG." (PMID 26106390, 2015). "In previous study the streptavidin interleukin-2 (SA-IL-2)-modified MB49 vaccine was effective against bladder cancer in a mouse model." (PMID 26566931, 2015). "With regard to bladder cancer, interest was stimulated after multiple investigators identified elevated IL-2 levels (as well as other cytokines) in urine of patients following BCG, suggesting an immunomodulatory effect of BCG." (PMID 22778725, 2012). "Since IL-2 plays a crucial role in the Th1 response, it will continue to be a source of interest for immunotherapy of bladder cancer." (PMID 22778725, 2012). "A small clinical study investigating systemic IL-2 administration effects on low-stage bladder cancer found a complete and partial response rate in 5 of 12 patients, though 2 patients discontinued therapy due to toxicity." (PMID 22778725, 2012). "In another study, DC obtained from human umbilical cord blood transfected with secondary lymphoid-tissue chemokine and the interleukin-2 gene, which used established bladder cancer celllines as the source of antigen, enhanced cytotoxicity against same bladder cancer cell lines." (PMID 28266813, 2017). "Interestingly, BCG-activated NK cells improved their degranulation against all the bladder cancer cells, indicating that this activation process is more efficient than just IL-2 activation." (PMID 26106390, 2015). "Next, we studied whether IL-2-stimulated NK cells could change their ability to recognize a panel of bladder cancer cells after exposure to BCG for four days." (PMID 26106390, 2015). "Thus, primary IL-2-activated NK cell lines were prepared from healthy donors and used as effector cells in degranulation experiments against the panel of bladder cancer cells." (PMID 26106390, 2015). "More recent animal and in vitro studies have investigated IL-2 transfecting dendritic cells (DCs), immobilized streptavidin-tagged bioactive IL-2 on the biotinylated surface of murine bladder mucosa, and development of a murine IL-2 surface modified bladder cancer vaccine." (PMID 22778725, 2012). "In addition, bioinformatic analysis such as BCG and IL-2 models for bladder cancer treatment could also be useful." (PMID 37366889, 2023).
bladder cancer (continued). "In previous studies, it has been shown that the granulocyte macrophage‐colony stimulating factor (GM‐CSF) or interleukin‐2 (IL‐2) surface modified MB49 bladder cancer stem cells (MCSCs) vaccine could induce a specific antitumor immunity and against bladder cancer in mice model respectively." (PMID 28205361, 2017). "In bladder cancer, lentinan is an isolated botanical drug metabolite that induces macrophage activation in a bladder cancer mouse model, promoting the proliferation of CD4+ and CD8+ T cells while upregulating the expression of IFN-γ and IL-2." (PMID 41458964, 2025). "Cytokines released in patients with bladder cancer treated with BCG include TRAIL (TNF-related apoptosis-inducing ligand), IL-2, IL-8, IL-18, IL-12, IFN-γ, and TNFα." (PMID 36119107, 2022). "More recent novel immunotherapy drugs (e.g., ALT-801 (a tumor-targeted IL-2) and ALT-803 (an IL-15 superagonist complex)) have been tested in bladder cancer with promising antitumor activity." (PMID 29358573, 2018). "In this study, we engineered two human bladder cancer cell lines (RT112 and EJ) to constitutively release human IL-2 by retroviral vector-mediated gene transfer." (PMID 10070868, 1999). "In the mouse bladder cancer model, OMV-PP induced increased serum levels of IFN-γ and IL-2." (PMID 38166929, 2024). "In previous studies, it has been shown that GM‐CSF or IL‐2 did not induce a specific antitumor immunity and against bladder cancer in mice model." (PMID 28205361, 2017). "The data further show that treating either IL-2-activated NK cells or freshly isolated NK cells with BCG did not affect the intensity of the response against several bladder cancer cell lines." (PMID 26106390, 2015).
non-Hodgkin lymphoma (24 papers, 2009 to 2026). Distinct from Hodgkin lymphoma both morphologically and biologically, non-Hodgkin lymphoma (NHL) is characterized by the absence of Reed-Sternberg cells, can occur at any age, and usually presents as a localized or generalized lymphadenopathy associated with fever and weight loss. "PTEN presence, BCL2 mutations, and low or undetectable baseline IL-2 levels were associated with improved patient survival following treatment with C + R, supporting a potential role for these biomarkers in guiding treatment selection for patients with indolent non-Hodgkin lymphoma." (PMID 39984775, 2025). "Polymorphisms in the interleukin (IL)-2 and IL-10 genes are known to be associated with susceptibility to different immune-dysregulated disorders and cancers such as non-Hodgkin lymphoma (NHL)." (PMID 28713071, 2018). "NK-92, first established in 1992, is an interleukin-2 (IL-2)-dependent immortal cell line derived from a patient with non-Hodgkin’s lymphoma." (PMID 41601640, 2026). "Early clinical investigations employing IL-2 as an adjuvant for CAR T cell therapy in non-Hodgkin lymphoma demonstrated an increase in the frequency of FOXP3+ Treg cells." (PMID 39697333, 2024). "When IL-2 is elevated in patients diagnosed with non-Hodgkin lymphoma, their survival rates are diminished." (PMID 38967887, 2024). "A study from 2021 confirmed that the IL2 gene variants rs2069762 and rs2069763 could be involved in the development of non-Hodgkin lymphoma (NHL)." (PMID 36233401, 2022). "Nineteen patients with relapsed or refractory (R/R) MM and low-grade non-Hodgkin lymphoma (NHL) were given intravenous (i.v.)IL-2 and PAM." (PMID 35740670, 2022). "A preliminary pilot study by Wilhelm’s team examined toxicity, in vivo activation of γδT cells, and anti-lymphoma efficacy of pamidronate/IL-2 in 19 patients with relapsed/refractory low-grade non-Hodgkin lymphomas (NHL) or MM." (PMID 25426121, 2014). "For example, preclinical observations have described a synergistic effect of IL-2 in combination with rituximab in both retuximab-sensitive and retuximab-insensitive non-Hodgkin lymphoma (NHL) xenograft models." (PMID 19809433, 2009). "However, in non-Hodgkin's lymphoma, IL-2, -4, -5, -12P70, -1β, -17A, -17F, -22, and TNF-α play critical roles in bacterial infections of the lungs." (PMID 37114211, 2023). "Wilhelm and coworkers first demonstrated that in vivo Vγ9Vδ2 T cell stimulation by Pam and low-dose IL-2 was safe and could induce objective tumor responses in patients with low-grade non-Hodgkin lymphoma (NHL, n = 11) and multiple myeloma (MM, n = 8)." (PMID 25686210, 2015). "Lenalidomide was shown to enhance Rituximab induced ADCC against non-Hodgkin lymphoma and B-cell chronic lymphocytic leukemia through enhanced CD4+ T cell dependent IL-2 release, resulting in augmented NK cell activation, granzyme B, and FasL release." (PMID 25972872, 2015).
anemia (23 papers, 2013 to 2025). A reduction in the number of red blood cells, the amount of hemoglobin, and/or the volume of packed red blood cells. "Childhood anemia also increases the susceptibility of children towards infection by its effects on defective Interleukin-2 (IL-2) and Interleukin-6 (IL-6) production and thus compromises immunity." (PMID 34521396, 2021). "Il2CD4 mice exhibited IL-2 Deficiency Syndrome24–26 characterized by severe anemia, splenomegaly, uncontrolled expansion of T cells associated with a reduction of Treg cells, and loss of B cells." (PMID 29549257, 2018). "Here we show that an enhanced NFATc1 activity induced by increased integrin-cAMP signaling plays a critical role in the dysregulation of Klf1 expression and thereby cause anemia in Il2-/- mice." (PMID 29515759, 2018). "Similar to our study, the IL2 class-specific AEs observed in these previous studies of simlukafusp alfa included pyrexia, anemia, transaminase increase or abnormal liver function tests, edema, and IRRs." (PMID 39140264, 2024). "Comparisons of patients with mild TB and mod-sev disease or anemia, demonstrated that Th1 (IL-2, IFN-γ, and TNF-α) as well as Th2 (IL-4, IL-13, and IL-10) and Th17 responses were higher in mild TB disease." (PMID 38162636, 2023). "AIHA, thought to be the primary cause of death in IL-2 and IL-2Rα-KO mice is caused by autoantibodies against RBC antigens and is measured by the frequency of antibodies bound to RBCs in combination with anemia severity." (PMID 33319815, 2020). "We have shown previously that IL-2 critically regulates BM erythropoiesis in a Treg-dependent manner, and restoration of Treg activity or abolition of IFN-γ activity significantly reversed anemia in Il2−/− mice." (PMID 29515759, 2018). "We have shown recently that Il2-/- mice develop severe anemia due to defects in KLF1 activity during BM erythropoiesis." (PMID 29515759, 2018). "Anemia requiring transfusion of 1 unit of packed red blood cells (PRBCs) was required during the second week of IL-2 therapy." (PMID 27144182, 2016). "One month following completion of high-dose IL-2 treatment, she was hospitalized for severe, symptomatic anemia and received 5 units of PRBCs." (PMID 27144182, 2016). "Previous studies in HIV patients have reported autoantibodies to several human proteins, including erythropoietin (EPO), interferon-α (IFN-α), interleukin-2 (IL-2), and HLA-DR, as potential mediators of anemia or immunosuppression." (PMID 26599070, 2015). "Among them, two cases were found to have anemia and elevated inflammatory indicators by laboratory examination, which may be related to the production of cytokines such as IL-2 and IL-6 by tumor cells." (PMID 39144665, 2024). "Thus, enhanced Fas-FasL activity as well as upregulated activity of other apoptosis-promoting molecules in IL-2-deficient erythroid cells results in increased cell death leading to anemia development in Il2−/− mice." (PMID 29515759, 2018). "Our findings suggest that NFAT hyperactivity is a key mechanism that blocks erythrocyte differentiation and promotes anemia development in Il2−/− mice, which might also be operative in inducing anemia in humans." (PMID 29515759, 2018). "Our observation about Nfat expression in erythrocytes suggests they might have a role to play in erythropoiesis, and the increased NFAT activity in Il2−/− erythroid cells could be one of the reasons that the Il2−/− mice suffer from severe anemia." (PMID 29515759, 2018). "For instance, IL-2 KO mice that have lower Treg frequency experience anemia." (PMID 30550561, 2018). "Il2 deletion in the CD4+ T-cell compartment resulted in characteristic IL-2 Deficiency Syndrome24–26 originally described in Il2KO mice and characterized by severe anemia, splenomegaly, uncontrolled expansion of splenic T cells associated with reduction of Treg cells and loss of B cells." (PMID 29549257, 2018).
anemia (continued). "Trend analysis of IL-2, IL-5, FGF, PDGF-bb, IL-17, CCL5, IL-4, IL-13, IFN-γ, IL-7 and TGF-β1 uncovered that as the severity of anemia increased, the concentrations of these inflammatory molecules decreased." (PMID 37143662, 2023). "Prior to starting the second week of IL-2, her Hgb was 8.9 g/dL and Hct was 26.8%, with mean corpuscular volume (MCV) of 89.3, consistent with anemia of chronic disease." (PMID 27144182, 2016). "As hypoxia is one of the stimulators of VEGF, the correction of anaemia (or anaemia-induced hypoxia) with EPO would counteract the pro-angiogenic actions of VEGF and reverse IL-2 resistance." (PMID 23305401, 2013). "Other markers ranked to separate anemia from non-anemia included IL-2, IL-1 receptor antagonist (RA), IL-13, IFN-γ, RANTES (CCL5) and IP-10." (PMID 38162636, 2023). "RBC precursor defects only became apparent in older IL-2Rα-KO mice, suggesting that BMF only mildly contributes to early anemia but may be relevant to late disease kinetics, despite BMF contribution to rapid disease in IL-2-KO mice." (PMID 33319815, 2020). "We have recently shown that mice lacking IL-2 signaling have strong defects in erythrocyte differentiation and they develop anemia very early in life." (PMID 29515759, 2018). "Mice lacking IL-2 also develop severe BMF contributing to anemia development." (PMID 33319815, 2020). "She did not recall any prior episodes of anemia during pregnancy or prior to/during recovery from her nephrectomy 10 years previously, and had never been transfused prior to the transfusion during the second week of high-dose IL-2." (PMID 27144182, 2016). "Since IL-2 is a Th1 type cytokine secreted by T cells and SHP2 plays an up-regulation role in the development and function of hematopoietic cells, the chemotherapy-induced anemia could be related to the development of immunosuppression and cytotoxicity on hematopoietic cells." (PMID 32038252, 2019).